TOX3 (TOX high mobility group box family member 3)
Diseases named in the same sentence as TOX3 in open-access papers (continued):
Sharing a sentence is not in itself a finding about the gene and the disease.
tumor (continued). "Overall, our study identified TOX3 as a key gene in the MAPK and EMT signaling pathways in HCC, and its overexpression confers significant proliferation and invasiveness to tumor cells." (PMID 38463397, 2024). "Consistent with a role for TOX3 in proliferation of tumor cells, knockdown of TOX3 in BT474 inhibits growth in culture, while knockdown of TOX3 in ZR-75-1 led to poor tumor formation in nude mice." (PMID 25632947, 2015). "Survival analysis within subgroups depending on ER status revealed that high TOX3 mRNA expression in patients with ER positive tumours resulted in shorter DMFS and OS than in patients with low TOX3 mRNA (p = 0.029 and p = 0.017, respectively)." (PMID 23270421, 2012). "The significantly lower TOX3 and LOC643714 expression in tumours expressing high Ki67 was due to the relatively high number of basal tumours expressing high Ki67." (PMID 23270421, 2012). "Compared with normal tissues, whether ABCG2, TOX3, or WDR5 is up-regulated in clinical metastatic and drug-resistant tumor specimens, and shows a strong prognostic value for OS and DFS in drug-resistant CRC patients." (PMID 37708089, 2023). "Fewer tumours are within the ER negative group and the effect of TOX3 mRNA level on survival was not statistically significant." (PMID 23270421, 2012). "Survival was compared between patients with tumours that expressed high mRNA levels (above average) of TOX3 or LOC643714 as opposed to low levels (below average)." (PMID 23270421, 2012). "Luminal A and B tumours, that are mainly ER positive, expressed significantly higher mRNA than ER negative basal tumours (TOX3 and LOC653714 mRNA vs. subtypes: p < 0.001 and p < 0.001, respectively)." (PMID 23270421, 2012). "Expression of LOC643714 correlated with that of TOX3 in ER negative tumours (r = 0.64, p < 0.001) but not in ER positive tumours (r = 0.13, p = 0.25)." (PMID 23270421, 2012). "PgR positive tumours also had significantly higher TOX3 and LOC643714 mRNA levels than PgR negative ones (p = 0.005 and p < 0.001, respectively)." (PMID 23270421, 2012). "Expression of TOX3 mRNA was compared to the rs3803662 genotype in the total set of tumours as well as in ER positive and ER negative tumours." (PMID 23270421, 2012). "The rs3803662 genotype may only affect expression of TOX3 and LOC643714 in certain tumour subtypes." (PMID 23270421, 2012). "We can only speculate that LOC643714 has a role in tumour development based on results similar to TOX3 but its mRNA is not translated and its function is unknown." (PMID 23270421, 2012). "Interestingly, two-thirds of the ERBB2 tumours were ER negative, yet they expressed significantly higher TOX3 mRNA than basal tumours (p = 0.02)." (PMID 23270421, 2012). "Additionally, there are no studies on the expression of TOX2 and TOX3 in CRC tumor tissues." (PMID 32393998, 2020). "According to the in-silico analysis, this mutation is not predicted to modify the folding or function of the TOX3 protein (PSIPRED and SIFT), but interestingly it is differentially expressed between the tumours." (PMID 24069272, 2013). "But there was lack of correlation between low mRNA levels of TOX3 and LOC643714 and high expression of Ki67 and low mRNA level of LOC643714 and negative ErbB2 status of the tumour as well as high histograde." (PMID 23270421, 2012). "Expression levels of TOX3 and LOC643714 were significantly higher in ER positive tumours than in ER negative tumours (p = 0.004 and p < 0.001, respectively)." (PMID 23270421, 2012). "This discrepancy between TOX3 and LOC643714 may possibly be due to fewer LOC643714 tumours than for TOX3, different distribution of available samples into subtypes, or the fact that there was not a correlation between TOX3 and LOC643714 in ER positive tumours." (PMID 23270421, 2012).
infection (3 papers, 2022 to 2024). The state of being infected such as from the introduction of a foreign agent such as serum, vaccine, antigenic substance or organism. "Therefore, we simultaneously targeted the putative PnPf2 paralogue SNOG_08565 (25.4% sequence identity) and SNOG_03067 (PnEbr1), which is co-expressed with PnPf2, ToxA, Tox1 and Tox3 high during early infection and has virulence regulating orthologues." (PMID 39312592, 2024). "The P. nodorum effector Tox3 is detected by Snn3, which results in the upregulation of defense-related transcripts, indicating that Snn3 likely functions in plant defense but is being manipulated by Tox3 to promote infection." (PMID 35587147, 2022). "To determine evidence of fitness penalty on Snn1 wheat, we used a digital PCR approach to compare the DNA biomass of SN15 (+) and (-) during infection of Snn1 (H086, H336 and H091) and snn1 (H213 and H324) wheat varieties deriving from the CxW population that lacked Tox3 and Tox2A sensitivity." (PMID 34990464, 2022).
metabolic disorder (1 paper, 2020). "In the present study, the risk genotype group, GG+GT, presented a higher rate of IR than the TT group in women with PCOS, indicating that TOX3 may contribute to PCOS through a metabolic disorder-related pathway." (PMID 32425888, 2020). "This genotype-phenotype study thus provides clues that THADA, INSR, TOX3, and DENND1A play a role in PCOS possibly through a metabolic disorder-related pathway." (PMID 32425888, 2020). "It suggests that THADA, INSR, TOX3, and DENND1A might play a role in PCOS through a metabolic disorder related pathway." (PMID 32425888, 2020).
neurodevelopmental disorder (1 paper, 2022). A behavioral and cognitive disorder with onset during the developmental period that involves impaired or aberrant development of intellectual, motor, or social functions. "TOX3 plays a role in shaping DNA and altering chromatin structure and while the protein has been shown to be a neuron survival factor, it is yet to be linked with neurodevelopmental disorders and specifically to RTT." (PMID 36232428, 2022).
TOX3 also shares sentences with these, for which no sentence is quoted: metabolic syndrome (2 papers); Obesity (2); ovarian carcinoma (2); Parkinson's (2); abortion (1); adenocarcinoma (1); benign breast disease (1); breast and ovarian cancer (1); clear renal cell carcinoma (1); cleft lip (1); colon cancer (1); hepatocellular carcinoma (1); Hyperglycemia (1); hyperlipidemia (1); Hypertension (1); prostate carcinoma (1); psychiatric disorder (1); squamous cell carcinoma (1); sterility (1); type 2 diabetes mellitus (1).